NLRP3 (NLR family pyrin domain containing 3)
Diseases named in the same sentence as NLRP3 in open-access papers (continued):
Sharing a sentence is not in itself a finding about the gene and the disease.
colorectal cancer (continued). "On the contrary, antagonists targeting NLRP3 or caspase-1 suppress the migration of colorectal cancer cells in vitro, and knockout of NLRP3 decreases liver metastasis nodes in vivo." (PMID 36932407, 2023). "By targeting NLRP3, miR-22 inhibits cell proliferation, migration, and invasion in colorectal cancer." (PMID 37715239, 2023). "A lower NLRP3 expression was seen in the colon tissue compared to paired healthy mucosa in colorectal cancer patients (log2 FC = 1.1, p < 0.01)." (PMID 35499706, 2022). "The reduced expression of NLRP3 in colorectal cancer (CRC) tissue holds a positive predictive value." (PMID 35804922, 2022). "The role of NLRP3 in gastrointestinal cancers seems to generally be pro-tumoral with exceptions in colorectal cancer where there are cases of anti-tumoral activity as well." (PMID 35877745, 2022). "By increasing the level of various inflammatory cytokines including IL-18, TNF-α, and TGF-β1, the NLR family pyrin domain–containing 3 (NLRP3) inflammasome can trigger metastasis in colon and colorectal cancer samples." (PMID 34992527, 2021). "To explore the role of Gal-NLRP3 in colorectal cancer, we first investigated the role of NLRP3 in the colorectal cancer cell line." (PMID 34955826, 2021). "The NLRP3 inflammasome was also activated in macrophages through the macrophage–colorectal cancer cell crosstalk that resulted in the accelerated migration of colorectal cancer cells and improved their metastatic ability." (PMID 34571825, 2021). "Ours for the first time so far showed that NLRP3 inflammasome is activated in colorectal cancer and its activation is concurrent with the progression of epithelial to mesenchymal transition and development of CRC." (PMID 34094030, 2021). "In this study, we have found that NLRP3 in the inflammatory microenvironment can promote the metastasis and invasion of colorectal cancer cells, which is an important factor in promoting colorectal cancer progression." (PMID 34955826, 2021). "For example, the activation of the NLRP3 inflammasome in macrophages that surround colorectal cancer tissue can drive cancer cell metastasis to the liver." (PMID 34457117, 2021). "Due to the contribution of adipose tissue to several biological processes and to cancer cachexia, we sought to investigate the activation of components of the NLRP3 inflammasome pathway in the two white adipose tissue depots in patients with colorectal cancer." (PMID 34630405, 2021). "Other studies in a mouse model of colorectal cancer suggest that activation of NLRP3 results in increased antitumor immunity, and in a thymoma model NLRP3 activation increased activation of CD8+ cells during chemotherapy." (PMID 33649199, 2021). "NLRP3 knockdown in colorectal carcinoma cells maintained the epithelial spindle-like morphology and decreased cell migration and invasion." (PMID 34571825, 2021). "Existing evidence suggests that inflammasomes such as NLRP3 can be activated by fatty acids and high glucose levels, leading to chronic intestinal inflammation and colorectal cancer." (PMID 33014529, 2020). "In this study, NLRP3 was found highly expressed in the tumor tissues of patients with colorectal cancer." (PMID 32435622, 2020). "Another study determined that NLRP3 expression was a prerequisite for epithelial-mesenchymal transition in colorectal cancer cells; suggesting the role of NLRP3 in promoting cell migration and proliferation during CRC." (PMID 32456012, 2020). "Data on the role of NLRP3 in colorectal cancer (CRC) pathogenesis is inconsistent, where some evidence suggests a pro-tumorigenic role for the inflammasome, while others identified that the inflammasomes protects against tumor." (PMID 31118894, 2019). "Some reports indicate that NLRP3 inflammasome activation and IL-18 signaling protect against colorectal cancer, whereas progression of breast cancer, fibrosarcoma, gastric carcinoma, and lung metastasis were shown to be supported by the inflammasome." (PMID 31118894, 2019).
colorectal cancer (continued). "Contrary to the effects of NLRP3 in the promotion of cancer, studies in colorectal cancer demonstrated that increased NLRP3 inhibits colorectal metastasis." (PMID 30631327, 2018). "Moreover, its treatment reduced colorectal cancer proliferation by modulating the NF‐κB pathway and Bax expression while suppressing Bcl‐2, cyclin‐D1, c‐myc, and NLRP3 expression." (PMID 40321606, 2025). "Interestingly, NLRP3-produced IL-1β induces the migration of colorectal cancer cells, and its activation in liver macrophages (Kupfer cells) decreases the metastasis of colorectal cancer cells." (PMID 40141358, 2025). "Moreover, activation of the hematopoietic NOD-, LRR-, and pyrin domain-containing protein 3 (NLRP3) inflammasome has been demonstrated to be crucial for PG–induced colorectal cancer development." (PMID 41155306, 2025). "Additionally, our previous research confirmed that IOP modulated the NLRP3 inflammasome pathway, inhibiting colorectal cancer progression." (PMID 40732305, 2025). "The mechanism of action of NLRP3 in colorectal cancer is still disputable." (PMID 38182564, 2024). "In colorectal cancer, 5-HT plays a role in promoting NLRP3 activation." (PMID 38523155, 2024). "The NLR family pyrin domain containing 3 (NLRP3) promotes the growth of colorectal cancer (CRC)." (PMID 38543085, 2024). "USP10 mediates the deubiquitination of NLRP3 to enhance its protein stability, which promotes the secretion of NLRP3-induced C–C motif chemokine ligand 2 and promotes the polarization of pro-tumorigenic M2-like macrophages in colorectal cancer." (PMID 39253578, 2024). "The data imply that NLRP3 plays a tumor suppressor role in colorectal cancer." (PMID 37715239, 2023). "However, Ping-wei-san showed beneficial effects in reducing colonic damage in patients with colorectal cancer, inhibiting inflammatory cytokine production and pathway activation of the NF-κB pathway and the NLRP3 inflammasome in mice." (PMID 37397480, 2023). "In addition, NLRP3 was found to suppress hepatic metastasis of colorectal carcinoma by increasing the production of IL-18, thereby promoting NK cell maturation and cytotoxicity." (PMID 37289257, 2023). "During the early stage of colorectal cancer, elevated IL-18 secretion facilitated by NLRP1/NLRP3/pyrin could protect against colorectal cancer through the promotion of epithelial barrier regeneration during the early stages of colorectal cancer." (PMID 35990696, 2022). "In addition, tumour-promoting inflammation mediated by the upregulation and activation of NLR family pyrin domain containing 3 (NLRP3) inflammasome in macrophages resulted in colorectal cancer and gastric cancer migration." (PMID 36428985, 2022). "Conversely, NLRP3 is also demonstrated to have anti-tumorigenic effects in colorectal cancer." (PMID 35754962, 2022). "The role of NLRP3 in colorectal cancer is controversial and seems to be a double-edged sword." (PMID 35877745, 2022). "Whether NLRP3 is involved in the progression and prognosis of colorectal cancer (CRC) remains elucidated and is the focus of the present study." (PMID 33821998, 2021). "Therefore, IL-18 signaling downstream of the NLRP3 inflammasome plays a central role in the protection against colorectal cancer progression." (PMID 34571825, 2021). "In addition, mice with NLRP3 knockout show an increase in colorectal cancer metastases in the liver." (PMID 34885171, 2021). "based on the evidence from our previous study with a rodent model of cachexia, we examined the activation of the NLRP3 inflammasome pathway in two adipose tissue depots obtained from patients with colorectal cancer and compared with that another inflammatory pathway, NF-κB." (PMID 34630405, 2021). "The activation of NLRP3 could promote the malignant behavior of colorectal cancer cells in the inflammatory microenvironment." (PMID 34955826, 2021).
colorectal cancer (continued). "Interestingly, inflammasome-independent NLRP3 has also been demonstrated to develop TGF-β-induced epithelial–mesenchymal transition (EMT) in colorectal cancer." (PMID 34571825, 2021). "Additionally, the NLRP3 inflammasome in Kupffer cells suppressed colorectal cancer metastatic growth in the liver by promoting the maturation of NK cells and tumoricidal activity mediated by IL-18." (PMID 34298833, 2021). "Therefore, in this study, we used NLRP3 as the starting point to investigate the target of Gal and its anti-colorectal cancer effect." (PMID 34955826, 2021). "Moreover, knockdown of NLRP3 was found to diminish the migration and invasion abilities of colorectal carcinoma cells." (PMID 34393801, 2021). "In patients with colorectal cancer, NLRP3 was found highly expressed." (PMID 32435622, 2020). "Indeed, in a mouse model of liver metastasis from colorectal cancers, NLRP3-/- mice showed reduced IL-18 expression and this was associated with increased liver metastasis." (PMID 33255437, 2020). "Indeed, many tumors and especially colorectal carcinomas (CRCs) develop as a result of a chronic inflammatory microenvironment mediated by pathologically sustained NLRP3 (NACHT, LRR, and PYD domains-containing protein 3) inflammasome activation." (PMID 33102234, 2020). "Notably, the natural compound schisandrin B has been reported to upregulate Smurf2 protein levels in colorectal cancer, while curcumin induces NLRP3-dependent pyroptosis in non-small cell lung cancer (NSCLC) (ncells by inhibiting Smurf2 ubiquitin ligase activity." (PMID 40978141, 2025). "Therefore, IL‐18 signaling downstream of the NLRP3 inflammasome may be critical in preventing colorectal cancer development." (PMID 40671401, 2025). "As NLRP3 may control colorectal cancer (CRC) metastasis by activating EMT." (PMID 40671401, 2025). "Furthermore, NLRP3 inflammasome dysfunction appears to increase tumor burden in colorectal cancer." (PMID 37715239, 2023). "Therefore, it is not surprising that delineation of molecular cross-talk between activation of NLRP3 inflammasomes and EMT-associated markers has become the center of research attention and can be an attractive strategy for reducing the risk of colorectal cancer progression." (PMID 34094030, 2021). "Galloflavin could inhibit the malignant behavior of colorectal cancer cells by targeting NLRP3." (PMID 34955826, 2021). "Therefore, we validated that NLRP3 played a tumor-promoting role in colorectal cancer." (PMID 34955826, 2021). "Therefore, NLRP3 plays an important role in the microenvironment of colorectal cancer." (PMID 34955826, 2021). "Inversely, knockdown of NLRP3 in colorectal carcinoma cells suppressed CRC cell migration in vitro and decreased the capacity of invasion." (PMID 34094030, 2021). "In colorectal cancer, cholesterol promoted colon carcinogenesis through activating the NLRP3 inflammasome and suppression of AMPKα in macrophages, resulting in significant increase of mitochondrial reactive oxygen species, which in turn enhanced the NLRP3 inflammasome activity." (PMID 32486083, 2020). "FL118 induces pyroptosis mediated by the NLRP3 inhibitor MCC950 and the caspase-1 inhibitor VX-765 attenuate the expression of NLRP3 and caspase-1 in colorectal cancer cells." (PMID 38654314, 2024). "Moreover, further research should be conducted to clarify how GLB suppresses colorectal carcinogenesis through means other than NLRP3 inhibition, which may lead to the elucidation of important mechanisms of inflammation-related colorectal cancer development and progression." (PMID 39519191, 2024). "Case reports have shown significantly decreased the expression levels of NLRP1, NLRP3, NLRC4, AIM2, and other inflammasomes in patients with colorectal cancer compared to healthy controls." (PMID 38756775, 2024).
colorectal cancer (continued). "In summary, our results identified NLRP3 as an integral functional target of HDAC2 and substantiated the NLRP3 pathway, in which HDAC2 governs pharmacological pyroptosis in colorectal carcinoma by modulating NLRP3 levels." (PMID 38804602, 2024). "They found that the mRNA expression of NLRC3 as an inflammation checkpoint; NLRP1, NLRP3 and NLRC4 as the components of inflammasome and AIM2 were all decreased in colorectal cancer." (PMID 34571825, 2021). "Recent studies reported higher NLRP3 and PYCARD protein expression in cancer tissues than in adjacent normal tissues from patients with laryngeal squamous cell carcinoma (LSCC) and colorectal cancer (CRC)." (PMID 34540671, 2021). "Finally, the activation of NLRP3 inflammasome, with consequent production of IL-1β, IL-18 and procaspase-1 activation which induces pyroptosis (i.e. a form of programmed cell death), showed an anti-tumoral effect preventing/inhibiting colorectal cancer development." (PMID 32107391, 2020). "NLRP3 mediated macrophage-colorectal cancer (CRC) cell crosstalk and achieved higher migration rates of CRC cells, whereas blocking NLRP3 signaling suppressed CRC cell migration in vitro and liver metastatic ability in vivo." (PMID 33613533, 2020). "We found that CAPE decreased NLRP3 inflammasome activation in BMDMs and THP-1 cells and protected mice from colorectal cancer induced by AOM/DSS." (PMID 32435622, 2020). "Several lines of evidence have shown that NLRP3-/- mice are more prone to develop colorectal cancer induced by azoxymethane/DSS, suggesting a protective role of NLRP3 inflammasome in tumorigenesis." (PMID 31200447, 2019). "In colorectal cancer cell lines, TNF‐α and TGF‐β induce EMT‐like changes either in a NLRP3/Snail1 axis‐dependent way (NLRP3 stands for ‘NOD‐like receptor family, pyrin domain containing 3’), or via an increase in expression of claudin‐1." (PMID 28599100, 2017). "As mention before, the NLRP3 inflammasome could play a positive role for protecting the colorectal cancer (negative effect on the aHR) in the late stage of chronic colitis." (PMID 38649928, 2024). "The NLRP3 inflammasome activates IL1β, which stimulates tryptophan hydroxylase 1 (TPH1, gene coding the 5-HT biosynthesis rate-limiting enzyme) transcription to increase 5-HT production in colorectal cancer cells, forming a positive feedback loop between 5-HT and NLRP3 signaling." (PMID 38523155, 2024). "Some studies have found that NLRP3 is a potential protective factor, such as the lack of NLRP3 inflammasome will increase the metastatic growth of colorectal cancer in the liver and the activation of NLRP3 inflammasome may suppress the growth of tumor cells." (PMID 35535346, 2022). "It has been shown in colorectal cancer that NLRP3 activation can enhance antitumor immunity by promoting NK cell activity and IL-18/IFN-γ signaling, whereas microbiota-driven dysregulation of NLRP3/GSDMD may instead support tumorigenesis through disrupted signaling." (PMID 41291696, 2025). "Lower levels of NLRP3, NLRP1, and AIM2 proteins were found in hepatocellular carcinoma (HCC), colorectal cancer (CRC), and gastric cancer (GC) compared to the adjacent normal tissue." (PMID 34298833, 2021). "NLRP3 expression, but not the NLRP3 inflammasome complex activation, was required for EMT in colorectal cancer cells." (PMID 32508821, 2020).
Hepatic steatosis (122 papers, 2013 to 2026). Steatosis is a term used to denote lipid accumulation within hepatocytes. "Experimental models demonstrate that NLRP3 deficiency confers protection against diet-induced hepatic steatosis in MASLD mice, reinforcing its pathogenic significance." (PMID 41530836, 2026). "In recent years, extensive research has focused on the role of inflammatory responses mediated by inflammasome NLRP3 in liver injury caused by metabolism-associated fatty liver disease." (PMID 39796282, 2025). "The NLRP3 inflammasome pathway in hepatocytes is activated in response to alcohol, and a deficiency in Nlrp3 mitigates liver steatosis and injury caused by chronic ethanol exposure." (PMID 38540172, 2024). "Controversially, the loss of NLRP3 in a murine model of MASLD ameliorated hepatic steatosis and protected macrophage recruitment." (PMID 38674122, 2024). "Silybin has been shown to inhibit endoplasmic reticulum stress and the activation of the NLRP3 inflammasome in mice with fatty liver disease associated with metabolic dysfunction fed a high-fat diet." (PMID 39061866, 2024). "It draws attention towards gut dysbiosis and NLRP3 inflammasome as therapeutic targets for treating environment-linked fatty liver diseases and other inflammatory disorders." (PMID 38093299, 2023). "Cardiolipin is effective in stimulating NLRP3 inflammasome through a ROS-independent signaling pathway, and its deficiency is protected against hepatic steatosis." (PMID 35350750, 2022). "A subsequent study found that SFA sources containing palmitic acid can activate NOD-like receptor family pyrin containing 3 (NLRP3) inflammasomes, which are linked to the development of liver steatosis." (PMID 35698522, 2022). "Our findings demonstrated that the suppression of NLRP3 inflammasome activation by an orally available small molecule inhibitor leads to the alleviation of the hepatic steatosis symptoms associated with NAFLD induced by a high-fat diet." (PMID 27075683, 2016). "Recent reports have implicated the involvement of the Nlrp3 inflammasome in the development of hepatic steatosis." (PMID 25216251, 2014). "Additionally, two other studies reported protective effects of Nlrp3 or Asc deficiency in the development of HFD-induced liver steatosis and hepatic insulin sensitivity." (PMID 37239938, 2023). "Therefore, the activation of the NLRP3 inflammasome is associated with liver disease progression from simple fatty liver to NASH with inflammation and fibrosis." (PMID 34203484, 2021). "Thus, the development of fatty liver disease in mice deficient in NLRP3 (Nlrp3−/−) or its essential components (Asc−/− and Casp1−/− mice) can be avoided if they consume a high fat or nutrient-deficient diet." (PMID 32194416, 2020). "In the animal module, NLRP3 deficiency protects against HFD-induced liver steatosis in mice." (PMID 33273997, 2019). "Thus, changes in gut microbiota could through attenuated levels of TMAO, LPS, and taurine conjugated bile acid have contributed to beneficial effects of NLRP3 deficiency on myocardial remodeling and liver steatosis in these mice on HFD." (PMID 33273482, 2020). "To investigate whether the preventive effect of SFN on hepatic steatosis was associated with the suppression of the NLRP3 inflammasome in vivo, we determined the expression levels of NLRP3 inflammasome components (including NLRP3, ASC, and caspase-1) in the livers." (PMID 27075683, 2016). "The compound effectively attenuated hepatic steatosis, inflammatory responses, and fibrotic progression in experimental models through dual modulation of NLRP3 and YAP signaling pathways." (PMID 41530836, 2026). "BAs bind to TGR5 to increase AHR expression and promote transcription of ACOX 1 and CPT 1 A by triggering CAMP-ERK pathway and inhibit NLRP3 activity by triggering CAMP-PKA pathway, while AHR also inhibit activation of NLRP3, thus inhibiting hepatic steatosis." (PMID 39944639, 2025).